PDK1 (pyruvate dehydrogenase kinase 1)
Diseases named in the same sentence as PDK1 in open-access papers (continued):
Sharing a sentence is not in itself a finding about the gene and the disease.
breast cancer (continued). "The effect of the co-inhibition of PDK1 on the growth and metastasis of breast cancer is still open to investigation." (PMID 33266219, 2020). "The use of PDK1 inhibitors can help block glycolysis activity and also limit maintenance of breast cancer stem cells." (PMID 31709180, 2019). "PDK1 silencing severely impairs the ability of breast cancer cells to metastasize to the liver, while their ability to form lung and bone metastasis is not affected." (PMID 31052256, 2019). "In breast cancer, PDK1 stimulates glycolytic activity to stimulate cancer cells to take on stemness traits." (PMID 31709180, 2019). "PDK1 is a essential component of PI3K signaling in breast cancer, and PDK1 inhibition can suppress breast cancer progression." (PMID 31139017, 2019). "For instance, it was reported that constitutively active Akt was not able to rescue the reduced anchorage-independent growth or the increased apoptosis resulting from downregulation of PDK1 in breast cancer cells MDA-MB-231." (PMID 31088502, 2019). "Possibly it also depends on which kind of cancer and which organ site cancer cells will colonize to, for instance, liver metastatic breast cancer cells showed increased glycolysis activity by activating PDK1 and thus inhibiting PDH23." (PMID 29700317, 2018). "Immunohistochemical analysis revealed the overexpression of PDK1 in more than 80% of breast cancer tissues samples examined." (PMID 29668719, 2018). "In agreement, our results showed that depletion of PDK1 decreased breast cancer cell glycolysis phenotype and thereby depressed BCSC maintenance in vivo and in vitro." (PMID 29106390, 2018). "Such Akt-independent PDK1 signaling pathways appear to play an essential role in the anchorage-independent growth of breast cancer cells during migration and invasion." (PMID 29668719, 2018). "Lastly, Akt-independent PDK1 activity was recognized as a critical element in breast cancer metastasis." (PMID 29668719, 2018). "To confirm this, we examined PDK1 expression in BCSCs purified from breast carcinoma cells through their mammosphere formation ability and ALDH+ cell sorting." (PMID 29106390, 2018). "In breast cancer, it was recently shown that PDK1 inhibition was able to re-sensitize PIK3CA-mutant cells to PI3Kα inhibitors through suppression of SGK1 and reduction of mTORC1 activity." (PMID 29064423, 2017). "In breast cancer in particular, PDK1 is the means by which upstream lesions such as PTEN, PIK3CA and ERBB2 boost their signal output and reach to Akt, rendering the cells resistant to PI3K pathway inhibitors." (PMID 29064423, 2017). "Breast cancer is the most common cancer type affecting women worldwide and amplification of the PDK1 genetic locus is correlated with low survival rates." (PMID 29064423, 2017). "The interaction PDK1–PLCγ1 is important for cancer cell invasion, in particular of breast cancer and melanoma cells." (PMID 28287465, 2017). "Both pharmacological and genetic inhibition of PDK1 in vitro have demonstrated its significance for all steps of breast cancer progression, and in vivo experiments display its role in growth and metastasis." (PMID 29064423, 2017). "Recent data indicate that alteration of PDK1 (Phosphoinositide-dependent kinase 1) contributes to the oncogenic PI3K signaling in breast cancer progression." (PMID 27527857, 2016). "In this work, we show that inhibition of the constitutively active kinase PDK1 overcomes resistance to PI3Kα inhibitors in PIK3CA-mutant breast cancer cells insensitive to PI3Kα inhibition." (PMID 27451907, 2016). "In severe combined immunodeficiency mice, PDK1-depleted human breast cancer cells form tumors more slowly and are defective in extravasation to the lungs after intravenous injection." (PMID 26684827, 2015). "A recent study found that the upregulation of PDK1 promotes breast cancer oncogenesis, increases breast cancer progression and cell migration, and promotes experimental metastasis." (PMID 26318166, 2015).
breast cancer (continued). "Knockdown of PDK1 inhibits spontaneous migration and epidermal-growth-factor-induced chemotaxis in breast cancer cells." (PMID 26684827, 2015). "For example, PDK1 downregulation can inhibit migration and experimental metastasis of human breast cancer cells." (PMID 25742010, 2015). "Our findings indicate that PDK1 is independently activated in breast cancer and not only as part of the PIK3CA pathway, suggesting that PDK1 plays a specific and distinct role from the canonical PIK3/Akt pathway and promotes oncogenesis independently of AKT." (PMID 24739482, 2014). "Our data implicate PDK-1 and downstream components of the PDK-1 signaling pathway as promising therapeutic targets for the treatment of breast cancer." (PMID 24739482, 2014). "Subsequent studies demonstrated the role of PDK1 in a variety of different cancers; in particular PDK1 appears to play a decisive role in the development of breast cancer." (PMID 24739482, 2014). "Activation of PPARβ/δ induces the transcriptional activity of several downstream genes in mammary carcinoma cells such as the survival factor PDK1/Akt, VEGF-A and 14-3-3-epsilon." (PMID 25260874, 2014). "Increased gene copy numbers of PDK1 have been found in 21% of breast cancer samples, and total PDK1 mRNA and protein have been observed to be overexpressed in the majority of human breast cancer." (PMID 22666248, 2012). "Overexpression of PDK1 promotes invasion and activation of matrix metalloproteinase, while downregulation of PDK1 inhibits migration and experimental metastases of human breast cancer cells." (PMID 22666248, 2012). "PDK1 and PPARδ co-associate in DMBA-induced mammary tumors, and PPARδ activates PI3K/PDK1 signaling in a diverse range of cell types to enhance survival and growth." (PMID 21297860, 2011). "PDK1 is a key regulator of the AGC protein kinase family, which includes the proto-oncogene AKT/PKB implicated in several malignancies, including breast cancer." (PMID 21297860, 2011). "Loss of miR-375 has also been reported in gastric, liver and breast cancers, and a putative tumor suppressor role has been linked to a failure to repress the oncogenic miR-375 targets JAK2, YAP, PDK1 and RASD1." (PMID 22132151, 2011). "The plot of differential expression against disconnectivity shows that the central molecules, i.e. those with highest disconnectivity, remain stably expressed or induced in cancer with the exception of ERK1 and PDK1, both up-regulated in breast cancer." (PMID 22123172, 2011). "Furthermore, it has recently been reported that PDK1 is overexpressed in several human breast cancers and that increased copy number of the gene encoding for PDK1 is associated with upstream pathway lesions and patient survival, highlighting the importance of PDK1 in cancer development." (PMID 20051961, 2010). "Parallel RNAi and compound screens have recently revealed that PDK1 is a critical determinant of sensitivity to tamoxifen in breast cancer cells MCF7." (PMID 20051961, 2010). "Tissue microarray analysis of human breast cancers was used to measure PDK1 expression in invasive tumors by IHC." (PMID 16551362, 2006). "Our finding that PDK1 is activated in a large percentage of invasive human breast cancers further suggests the importance of the PDK1 signaling pathway to the metastatic phenotype." (PMID 16551362, 2006). "The presence of increased PDK1 expression in the majority of invasive breast cancers suggests its importance in the metastatic process." (PMID 16551362, 2006). "As a measure of the significance of PDK1 expression in breast cancer invasion, paraffin sections of malignant and benign breast cancers were examined for PDK1pSer241 expression." (PMID 16551362, 2006). "This is the first report demonstrating phosphorylation of PDK-1 is frequently elevated in breast cancer with concomitantly increased phosphorylation of downstream kinases, including AKT, mTOR, p70S6K, S6, and Stat3." (PMID 16288304, 2005).
breast cancer (continued). "Breast cancer tissues, which revealed moderate to high level of PDK-1 phosphorylation (scores 2 and 3), were grouped as positives and were observed in 72 out of 89 (80.9%) invasive breast tumours." (PMID 16288304, 2005). "In our both studies, however, similar findings were obtained regardless the source of breast cancer cells and thus confirmed the importance of PDK-1/AKT/mTOR/p70S6K activation in breast cancer." (PMID 16288304, 2005). "First, we showed that the phosphorylation PDK-1 at S241 was elevated in both human breast cancer cell lines compared to normal or immortalised mammary epithelial cell HMEC." (PMID 16288304, 2005). "Notably, PDK3 expression is elevated in breast cancer tissues, akin to PDK1, and is induced by HIF-1α, exhibiting increased expression levels." (PMID 41465397, 2025). "To fully elucidate the role of PDK1 in breast cancer, we first investigated whether PDK1 can promote the progression of breast cancer." (PMID 38560503, 2024). "In addition, studies have reported that PDK1 is involved in breast cancer progression, chemotherapy resistance, and distant metastasis, although controversies remain." (PMID 38560503, 2024). "We quantified the mRNA level of HIF-1α in breast cancer cells using qRT-PCR to clarify whether the regulatory mode of PDK1 on HIF-1α belongs to pre-transcriptional regulation or post-transcriptional regulation." (PMID 38560503, 2024). "Results showed that PDK1 was highly expressed in breast cancer." (PMID 38560503, 2024). "HIF-1α target pyruvate dehydrogenase kinase 1 (PDK1) is required for liver metastasis, and HIF-1α activity and PDK1 expression are elevated in liver metastasis of breast cancer patients, indicating that PDK1 is a key regulator of breast cancer metabolism and metastasis potential." (PMID 39588377, 2024). "Compared with normal people, breast cancer patients had higher expression of PDK1." (PMID 38560503, 2024). "Having established that PDK1 promoted the proliferation and migration of breast cancer cells in vitro, we further investigated whether PDK1 affects tumor growth in vivo." (PMID 38560503, 2024). "This study aims to elucidate how PDK1 promotes breast cancer progression." (PMID 38560503, 2024). "Using CancerMinea, a literature-based resource, we summarized that PDK1 might behave as an oncogene in many cancers, including breast cancer." (PMID 38560503, 2024). "To determine whether the high expression of PDK1 affected the malignant behavior of breast cancer cells, we generated the PDK1 stable knockdown cell line MCF7-sh and PDK1 stable knockout cell line BT-549-KO through sh-RNA interference and sgRNA knockout." (PMID 38560503, 2024). "Also, the immunohistochemical analysis indicated that PDK1 expression was higher in the human breast cancer tissues than in the adjacent normal tissues (n = 19)." (PMID 38560503, 2024). "Under hypoxic conditions, the H19/let-7/HIF1 signaling-mediated PDK1 could control glycolysis and further add to breast cancer stem cell maintenance." (PMID 37821504, 2023). "They show that, under hypoxia, PDK1 is needed to reprogram breast cancer cells toward stemness." (PMID 36768150, 2023). "To further explore whether histone modification was involved in the regulation of PDK1 expression, we carried out a correlation analysis between levels of PDK1 and HDACs in breast cancer samples from the TCGA dataset." (PMID 35892859, 2022). "To further study the roles of PDK1 and miR-148a in breast cancer development, we carried out GSEA analysis in breast cancer samples from the TCGA dataset, and found that PDK1 was positively correlated with TGF-BETA signaling (NES = 1.55, p value < 0.05, FDR q < 0.2)." (PMID 35892859, 2022). "Also, other studies reported that overexpression of PDK1 enhances the initiation of breast cancer, while suppression of PDK1 expression leads to the inhibition of breast cancer growth as seen in 7b and 7b group." (PMID 35164019, 2022).
breast cancer (continued). "Thus, potential pAKT regulators with previously reported relevance in breast cancer such as PDK1 or PTEN should be investigated in forthcoming studies." (PMID 35329936, 2022). "Importantly, miR-148a targeting PDK1 regulated breast cancer cells glycolysis, invasion, epithelial-mesenchymal transition (EMT) and Adriamycin resistance." (PMID 35892859, 2022). "We speculated that miR-148a increased breast cancer cell treatment response to Adriamycin through PDK1." (PMID 35892859, 2022). "However, the role and mechanism of epigenetic change in regulating PDK1 in breast cancer remains to be elucidated." (PMID 35892859, 2022). "In addition, the expression of key glycolysis genes GLUT1, HK2 and PDK1 was detected in breast cancer cells overexpressing HIF-1α after HNK treatment." (PMID 35350760, 2022). "Importantly, PDK1 is highly expressed in cancers including breast cancer, non-small cell lung cancer and pancreatic cancer, and it functions as an oncogene." (PMID 35264067, 2022). "In CAIX-suppressed breast cancer cells, let-7 miRNAs are upregulated while Lin28 protein levels decreased, leading to suppressed PDK1 activity and attenuated phosphorylation of PDH at Ser-232, which results in increased OXPHOS but reduced glycolysis and lactate production." (PMID 34572067, 2021). "Previous studies reported that the silencing of PDK1 or DCA treatment causes a metabolic shift from glycolysis to OXPHOS in different types of cancer including head and neck cancer, clear-cell renal cell carcinoma and breast cancer." (PMID 34439291, 2021). "In order to elucidate the pathway by which SIPA1 modulates the expression of glycolysis-related genes and PDK1, we analyzed RNA-seq data from two pairs of breast cancer cell lines: parental and SIPA1-knowndown MDA-MB-231 cells and parental and SIPA1-overexpressing MCF7 cells." (PMID 35096814, 2021). "ETV4 knockdown also downregulated HK2, LDHA and PDK1 protein levels in breast cancer cells." (PMID 34052833, 2021). "PDK1 could also affected the progression of multiple types of cancers, such as breast cancer, gastric cancer, and CRC." (PMID 33029299, 2020). "Moreover, for coping mechanisms against stress during metastasis, PDK1 mediates the adaptability of breast cancer cells metastasizing to the liver." (PMID 32039832, 2020). "By binding miRNA let-7 higher expression of H19 in hypoxia promotes the release of HIF-1α in hypoxic breast cancer stem cells eventually resulting in elevated expression of pyruvate dehydrogenase kinase 1 (PDK1) and consequently enhanced glycolysis and stemness." (PMID 32640630, 2020). "In addition, overexpression of PDK1 has been reported in multiple myeloma, acute myeloid leukemia, breast cancer and OS." (PMID 32039832, 2020). "PDK1 downregulation inhibits migration and metastasis of human breast cancer cells." (PMID 31139017, 2019). "Similarly, stable downregulation of PDK1 inhibited migration of the breast cancer cell line MDA-MB-231 and metastasis formation upon implantation of cells in immunodeficient mice." (PMID 31088502, 2019). "Importantly, pharmacological inhibition using GSK2334470 or shRNA-mediated knock-down of PDK1 decreased the viability, motility and malignancy of breast cancer cells in both cell culture and mouse models." (PMID 29668719, 2018). "Here, we show that pyruvate dehydrogenase kinase 1 (PDK1) is enriched in breast cancer stem cells (BCSCs), whereas depletion of PDK1 remarkably diminishes ALDH+ subpopulations, decreases stemness-related transcriptional factor expression, and inhibits sphere-formation ability and tumor growth." (PMID 29106390, 2018). "To identify further whether PDK1 is the potential downstream targets of H19, we first examined PDK1 expression upon H19 knockdown in breast cancer cells." (PMID 29106390, 2018). "In addition, P4HA1 expression significantly correlated with mRNA levels of LDHA and PDK1 in human breast cancer tissue." (PMID 30367042, 2018).
breast cancer (continued). "Accordingly, H19 and PDK1 expression exhibits strong correlations in primary breast carcinomas." (PMID 29106390, 2018). "PDK-1 may be an important therapeutic target in claudin-low breast cancer to prevent metabolic reprogramming and inhibit accelerated tumor growth associated with exercise." (PMID 29254140, 2017). "Consistent with a role for PDK1 in tumorigenesis, PDK1 overexpression and increased copy number in breast cancer has been shown to correlate with upstream lesions such as PTEN loss, PIK3CA mutation and EGFR amplification, and resulted in increased tumour growth, cell motility and poor prognosis." (PMID 27199173, 2016). "PI3K signaling appears to depend upon PDK1 rather than AKT in several breast cancer cell lines harboring the H1047R mutation in PIK3CA, and thus it remains to be seen if a similar mechanism exists in the L3.3 model." (PMID 22952903, 2012). "Further, although PDK-1 is one of the crucial downstream targets of PI3-K signalling and a key upstream kinase of AKT, it remains unclear whether PDK-1 is activated in primary breast cancer tissues." (PMID 16288304, 2005). "In addition, consistent results were obtained by using Western blottings and AKT kinase assay in which the phosphorylation levels of PDK-1 were significantly elevated in both human breast cancer cell lines, but at basal level in normal primary HMEC." (PMID 16288304, 2005). "Phosphorylation of EGFR and the remaining kinases were all correlated with PDK-1 phosphorylation (P<0.05), suggesting that EGFR might be one of the upstream regulators whereas other remaining kinases are downstream of PDK-1 pathway in breast carcinoma." (PMID 16288304, 2005). "Moreover, phosphorylated PDK-1 was predominately cytoplasmic localised, which was in close agreement with other finding suggested that retention of PDK-1 in cytoplasm provides close proximity in signalling its downstream targets in breast carcinomas." (PMID 16288304, 2005). "Taken together, our data thus suggest PDK-1 might play an important role in pathogenesis of breast carcinomas." (PMID 16288304, 2005). "In breast cancer (BC), PDK1 is genomically amplified and overexpressed, correlating with advanced tumor stage and poor prognosis." (PMID 40676293, 2025). "Furthermore, PDK1 plays a role in the growth and survival of human breast cancer cells." (PMID 38951817, 2024). "Thus, this study investigated whether SNH could induce mitochondrial dysfunction through ROS overgeneration and inactive the PDK1-AKT pathway to induce apoptosis of breast cancer cells in vitro and in vivo." (PMID 36900408, 2023). "To clarify the mechanism of epigenetic modification in regulating PDK1 in breast cancer, we address following questions: Firstly, to explore whether PDK1 expression is dysregulated in breast cancer and the aberrant expression of PDK1 is regulated by histone deacetylase 2 (HDAC2) and EZH2." (PMID 35892859, 2022). "However, the role of miR-148a/PDK1 for therapeutic effects in breast cancer is unclear." (PMID 35892859, 2022). "In summary, these results indicate that histone modification participates in the regulation of PDK1 by inhibiting miR-148a, and the existence of the HDAC2/EZH2/miR-148a/PDK1 regulatory axis may be important in breast cancer development and therapeutic resistance." (PMID 35892859, 2022). "However, the role and mechanism of PDK1 in breast cancer development remains to be elucidated." (PMID 35892859, 2022). "Thus, we hypothesized that epigenetic modification regulates the expression of miR-148a, and finally that miR-148a directly combines with PDK1 to regulate the development of breast cancer." (PMID 35892859, 2022). "But, the mechanism of epigenetic modification in regulating PDK1 remains unclear in breast cancer." (PMID 35892859, 2022). "Finally, to verify whether miR-148a and PDK1 are involved in cell chemoresistance, metastasis, proliferation, and apoptosis in breast cancer cells." (PMID 35892859, 2022).